EGFR (epidermal growth factor receptor)
Diseases named in the same sentence as EGFR in open-access papers (continued):
Sharing a sentence is not in itself a finding about the gene and the disease.
tumor (continued). "Taken together, our results suggested that IGF2BP3 might promote tumor cell proliferation and tumorigenesis via activation of the EGFR signaling pathway." (PMID 37658049, 2023). "In general, the distribution of EGFR expression in normal tissues appears homogeneous in intensity and spatially ordered, whereas it demonstrates heterogeneous staining intensity and spatial disorder in tumor tissues." (PMID 36875185, 2023). "However, our results suggest that anti-cancer strategies targeting EGFR signaling in cancer vasculature should take into account the expression of NOVA2-mediated AS isoforms in tumor ECs as potential mechanisms of resistance." (PMID 37175811, 2023). "EGFR is a complex protein that plays roles in many aspects of tumor growth and metastasis." (PMID 37720348, 2023). "In the xenografted tumor experiments, gefitinib was more effective in the absence of hormones, owing to the inverse correlation between AR signaling activity and EGFR signaling activity associated with HS3ST1 expression." (PMID 37463954, 2023). "When inhibition of ATP binding to EGFR occurs, there is a block in the process of auto-phosphorylation and stimulation of downstream signaling pathways, resulting in reduced cell proliferation and apoptosis induction in tumor cells." (PMID 38090376, 2023). "There may be various subclones of cancer cells, including those that are either sensitive or resistant to EGFR-TKIs within a single tumor." (PMID 36835536, 2023). "Importantly, sialyltransferase inhibition combined with EGFR antibodies was also effective in reducing the tumor load in a xenografted in vivo model." (PMID 37346044, 2023). "miR-34a is downregulated in GBM, and, if expressed in tumor cells, it causes suppression of cell proliferation and invasion, controls GSC differentiation, stem-like traits, and cell cycle arrest by targeting Notch1, Notch2, CDK6, EGFR, and c-Met." (PMID 37371047, 2023). "Notably, has-miR-34a-5p is a tumor suppressor that targets the epidermal growth factor receptor (EGFR) and is often lost or reduced in NSCLC." (PMID 36979715, 2023). "Here, we found a significant positive correlation between ERK5 and EGFR, implying ERK5 might serve as a crucial mediator to link EGFR alterations and increased tumor cell proliferation." (PMID 36720864, 2023). "Moreover, the EYA3 inhibitor benzarone blocks the transcription complex formation, MMPs, VEGFD, and EGFR expression, as well as tumor growth, and neoplastic cell invasion capacity in mouse tumor xenograft and in vitro cell models." (PMID 38069210, 2023). "Despite similar tumor mutational burden, metastatic sites displayed significantly higher ITH than primary ASCs (P = 0.0059 by Wilcoxon rank-sum test) and the similar result was observed in the EGFR-positive ASCs subgroup (P = 0.018)." (PMID 37634047, 2023). "In addition to having greater resistance to paclitaxel and docetaxel than their parental cells, cell lines that are resistant to EGFR inhibitors also have a higher capacity to initiate tumours." (PMID 37441599, 2023). "This increased TCR-Vβ clonality upon EGFR-TKI acquired resistance may reflect altered tumour responsiveness, serving as the cellular basis for immunotherapy." (PMID 38087217, 2023). "A recent study revealed that in contrast to dioxin-like chemicals, the treatment of human epithelial cells with PAHs including B[a]P results in an auto-/paracrine activation of EGFR, which can be an important contributing factor in AhR-mediated tumor promotion." (PMID 37696458, 2023). "Based on the findings of this study and those of previous studies, we speculated that suppressed EGFR expression inhibits EGFR and alters the sensitivity of tumour cells to MTX." (PMID 36611218, 2023). "Considering this trend, our results may support the importance of somatic mutations in NMIBC recurrence and the fact that somatic mutations in EGFR and TERT have a prognostic value for tumour recurrence in NMIBC." (PMID 37892022, 2023).
tumor (continued). "It is possible that these single biomarkers do not comprehensively reflect the characteristics of the tumor microenvironment in EGFR‐mutated NSCLC, resulting in poor predictive performance." (PMID 37723837, 2023). "Comparing rEBUS and transbronchial biopsy to subsequent surgical specimens revealed a 3% (n = 56) false negative rate among transbronchial biopsies for EGFR mutational analysis, a direct result of low tumor cell quantity in the associated specimens." (PMID 36980426, 2023). "In terms of predictive effect, only tumor HER3 mRNA expression may be a predictive biomarker for anti-EGFR therapy in RAS wt patients." (PMID 37974093, 2023). "Overall, MYL1 facilitates tumor metastasis and correlates with tumor immune infiltration in HNSCC and these effects may be associated with the EGF/EGFR pathway." (PMID 37679666, 2023). "Therefore, multiple roles of exosomal EGFR in metastasis formation and tumor immunity has been described." (PMID 37114127, 2023). "Abnormal expression and overactivation of RTKs, including vascular endothelial growth factor receptor (VEGFR), epidermal growth factor receptor (EGFR), and platelet-derived growth factor receptor (PDGFR) are associated with tumor invasion, metastasis, and tumor angiogenesis." (PMID 36818331, 2023). "In recent anti-cancer therapy, epidermal growth factor receptor tyrosine kinase inhibitors (EGFR-TKIs), such as gefitinib and erlotinib, have been used as a powerful therapeutic strategy to block tumor growth by binding certain parts of EGFR and have improved the survival rates in tumor patients." (PMID 36768961, 2023). "In the future, developing therapeutic regimens that target TAMs, such as interfering with TAM-related pathways, reducing infiltration of TAMs, and reprogramming the macrophage phenotype, could enhance the anti-tumor effect of EGFR-TKIs." (PMID 37649478, 2023). "Moreover, we showed that silencing of either LAMC2 or EGFR generated direct opposite effects on colony growth, cell cycle progression, cell activity, apoptosis, and tumor growth." (PMID 37542131, 2023). "Recent data suggest certain resistance to anti-EGFR agents in MSI-H tumours." (PMID 37377686, 2023). "Notably, the phosphorylation of EGFR activated diverse intracellular processes, such as accelerating cell proliferation and invasion, suppressing apoptosis and stimulating tumor angiogenesis." (PMID 36717944, 2023). "Follow-up CT tumor images have a fundamental role in response evaluation to EGFR-TKIs." (PMID 37730961, 2023). "In addition, anti-EGFR antibodies in mice brains inoculated with SW900-BM-GFl cell line confirmed the increased expression of EGFR in the zone of the tumor formation." (PMID 37311043, 2023). "Therefore, the early prediction of tumor progression in patients who receive EGFR-TKIs can facilitate patient management and development of treatment strategies." (PMID 36670497, 2023). "The benefit of first-line chemotherapy plus cetuximab or panitumumab in L-sided mCRC has been clearly demonstrated, while clinical evidence on the role of primary tumor site in predicting benefit from EGFR inhibitors in pretreated mCRC patients is still limited." (PMID 36895480, 2023). "Moreover, EGFR-positive tumor-derived EVs promote angiogenesis by reprograming TECs into VEGF-secretion phenotype." (PMID 36671802, 2023). "Correlating MD to NE tumor regions harboring EGFR amplification/CDKN2A deletion offers a means to assess regional cell proliferation, and identifying foci of cell proliferation enables a potential translational capability to implement targeted localized therapies." (PMID 37770427, 2023).
tumor (continued). "CD73 was found high in EGFR-MT NSCLC tumor cells, which may be a novel immune-relevant drug target to inhibit the growth of tumors." (PMID 36949948, 2023). "Furthermore, the analysis of the CN status of such samples revealed that the specimens with multiple copies of EGFR gene have a strong tendency to display low gain increase in CBX3 CN (80% of the samples compared to 5% of tumor with EGFR gene diploid)." (PMID 37633946, 2023). "Alternatively, the Ki-67 level was clearly lower in the EGFR alteration group, and there may be a significant difference in surgical outcomes and tumor aggressiveness." (PMID 37744696, 2023). "Furthermore, NEDD4L has been proved to act as a tumor suppressor through regulating EGFR, TGFβ, and Wnt signaling pathways, and the lower NEDD4L level showed poor prognosis in a variety of cancers clinically." (PMID 37495186, 2023). "Note that we did not observe a correlation between local tumor control and EGFR mutation in this study." (PMID 36676186, 2023). "Possibly, tumor heterogeneity might lead to an under- or overestimation of EGFR-expression and thus to a suboptimal delivery of the compound in vivo." (PMID 36879012, 2023). "In summary, ARID1A serves as the essential tumor suppressor in EGFR-mutant LUAD, while loss of ARID1A expression leads to the extensive activation of oncogenic pathways and enables tumor cells to acquire a more aggressive phenotype, finally resulting in the progression of the disease." (PMID 36869329, 2023). "Therefore, we assessed CD73 as a potential target to inhibit EGFR-EMT-related tumor cell invasion, as a prognostic parameter, and as a predictive marker of response to Cetuximab treatment." (PMID 37620936, 2023). "The different benefit from anti-EGFR according to primary tumor site in RAS/BRAF wt mCRC patients may be also explained by a heterogeneity of primary resistance profile." (PMID 36895480, 2023). "There are significant correlations between tumor grade on the one hand and EGFR overexpression." (PMID 38974258, 2023). "Collectively, our results suggest that in chemoresistant HNSCC patients, rCAF is the main supplier of TGFα in the tumor microenvironment, which may affect cancer cell chemoresistance via the TGFα-EGFR paracrine signaling." (PMID 37821657, 2023). "Interestingly, both EGFR TKIs were ineffective despite high EGFR expression as assessed by IHC in most tumor samples." (PMID 37298116, 2023). "Thus, to replace protein-based radiotracers for the visualization of EGFR-positive tumor lesions by a radiopeptide, the next step is to develop or identify a suitable peptidic receptor ligand that exhibits a sufficiently strong EGFR interaction profile." (PMID 37259420, 2023). "Furthermore, when phosphorylation of major tumor-promoting phosphorylation signals was examined, examined, the phosphorylated levels of EGFR, AKT, and ERK1/2 were markedly reduced." (PMID 37204253, 2023). "We hypothesized that the hidden information about tumor genetic alterations in the follow-up CT images after EGFR-TKIs therapy can be identified by the image radiomic features." (PMID 37730961, 2023). "EGFR-TKIs mainly play cytotoxic roles through G1 phase arrest, while pemetrexed works through S phase arrest, suggesting that the two can play a role in different tumor cell populations, thereby improving overall clinical efficacy." (PMID 36997925, 2023). "By contrast, the positive controls tested under identical conditions, [125I]I-hEGF and hEGF demonstrated the expected high EGFR-specific tumor cell uptake (33.6% after 1 h, being reduced to 1.9% under blocking conditions) and affinity (IC50 value of 15.2 ± 3.3 nM)." (PMID 37259420, 2023). "Besides affecting cancer cell signaling, EGFR TKIs were also known to affect T-cell tumor antigen recognition, T-cell activation, and tumor infiltration of immune cells." (PMID 37631380, 2023).
tumor (continued). "Activation of the PI3K‐AKT‐mTOR pathway in tumours is due to point mutations or amplifications of kinases (PIK3CA, AKT and MTOR), upstream receptor tyrosine kinases (epidermal growth factor receptor [EGFR], HER2, MET and FGFR) or small GTPases of the RAS family (HRAS, KRAS and NRAS)." (PMID 37877351, 2023). "EGFR-targeted chitosan NPs showed, in a more recent study, a consistent and preferential tumor targeting ability with rapid plasma clearance and the presence within the tumor up to 96 h." (PMID 37754880, 2023). "We demonstrated that RAS ctDNA status might be a valuable biomarker for detecting early tumour response and predicting benefit to anti-EGFR therapy." (PMID 37488448, 2023). "One possible explanation for the observed genotypic shift from EGFR-mutant to wild type might be due to spatial heterogeneity of the tumor, which could result in an uneven distribution of genetic subpopulations within a single tumor or across disease sites." (PMID 37503313, 2023). "Then, we asked whether the 01_cysEGFR and 06_cysEGFR peptides could be used for in vivo analysis of tumor tissues expressing EGFR." (PMID 37048151, 2023). "A correlation has been found between high lnc-EGFR expression and increased tumor size, which suggests that lnc-EGFR may play a crucial role in Treg differentiation and the suppression of antitumor T cell responses in CRC patients." (PMID 37760852, 2023). "But after literatures investigation about the optimal timing of immunotherapy and the potential impact of EGFR-TKI on tumor microenvironment, we prone to believe that the earlier treatment of immunochemotherapy after EGFR-TKI resistance, the better therapeutic effect would be observed." (PMID 37488517, 2023). "We present in this article a mechanistic model built based on those guidelines with the additional validation step (fifth step), integrating multiscale phenomena, with a context of use to predict tumor evolution and disease progression over time of EGFR-mutant LUAD patients treated with gefitinib." (PMID 37524705, 2023). "Analysis of the identified candidates, along with previously published data on interactors obtained by other methods, indicates the presence of a significant number of indirect interactions between PON2 and EGFR and, consequently, possible regulation of tumor growth with mutant EGFR involving PON2." (PMID 36653584, 2023). "Taken together, these findings indicate that cfDNA-based tumor mutation load and VAF may serve as potential biomarkers of responses and clinical benefits for EGFR 20ins-postive NSCLC." (PMID 37308490, 2023). "Based on these results, we examined the effect of EGFR inhibition on tumor extravasation." (PMID 37649607, 2023). "These cancer therapeutic drug nominations (both the heterocyclic chromenes and the sulfur-integrating derivatives) are enabled to inhibit the overexpression of EGFR (epidermal growth factor receptor), which triggers the emergence of numerous tumor subtypes (notably colon, breast, and ovarian)." (PMID 38069037, 2023). "Conversely, PTPN12 acts as a tumor suppressor gene through the regulation of EGFR expression." (PMID 37333450, 2023). "For patients without activating mutations in the downstream effectors of the epidermal growth factor receptor (EGFR) pathway and a left‐sided tumour, addition of an anti‐EGFR antibody to chemotherapy has shown promising results with median overall survival (OS) of 30–33 months." (PMID 37604687, 2023). "Therefore, tumor cells that over-express EGFR can be targeted for early detection of cancers by combining a fluorophore with molecules that display specific binding for EGFR." (PMID 41551238, 2023). "The expression level of EGFR is closely related to clinical prognosis; therefore, it may be a promising target for tumor immunotherapy in NSCLC." (PMID 36982500, 2023). "This case suggests that osimertinib could be an acceptable option for tumor control during pregnancy in EGFR-mutant NSCLC." (PMID 37035182, 2023).
tumor (continued). "Moreover, M2 TAMs were found less in the tumor stroma of EGFR-MT NSCLC compared with EGFR-WT in one study." (PMID 36949948, 2023). "Further, the ex vivo confocal analysis of TNBC xenografts confirmed the higher EGFR targeting ability of 01_cysEGFR peptide than that of 06_cysEGFR peptide, as shown by the co-localization of peptides with the EGFR receptor expressed in tumor tissues." (PMID 37048151, 2023). "Furthermore, the effect of the tumor side on treatment outcomes was larger for anti-EGFR-based treatment than for anti-VEGF-based treatment." (PMID 37760572, 2023). "Patients who test negative for PD-L1 may benefit more from a combination of PD-1 and EGFR inhibitors, likely because EGFR pathway inhibition alters the immune structure of the tumor microenvironment." (PMID 38293699, 2023). "AICAR reduced EGFR-mutant tumour cell growth by inducing DNA damage and apoptosis." (PMID 36810913, 2023). "PD-L1 or PD-1 as markers of EGFR signal suggested that EGFR mediates tumor immune escape." (PMID 37420173, 2023). "In contrast, in the presence of anti-CD20 mAb or anti-EGFR mAb, hnCD16FR-iNK cells co-cultured with specific antigen-expressing tumor cells induced a significant increase in proportion to the tumor cells killed, exhibiting a remarkable enhancement of antigen-specific cell lysis activity." (PMID 37316891, 2023). "Rebiopsy upon tumor progression revealed loss of BRAF V600E and emergence of EGFR C797S." (PMID 36765799, 2023). "Compared to wild-type tumours, RE tumours displayed a notably lower increase in oxidative stress-related nitrotyrosine and 8-hydroxydesoxyguanosin (8-OhdG) but elevated levels of phosphorylated EGFR (EGFR ~ P)." (PMID 37460712, 2023). "Focusing on only one type of EGFR-altered tumor (EGFRvIII deletion) may be insufficient in the battle against the complex heterogeneity of GBM." (PMID 37446288, 2023). "Furthermore, the classifier was also consistent with tests in tumor tissue for identification of response to EGFR-TKI treatment." (PMID 36902280, 2023). "The expression of EGFR was reduced in tumor xenografts from the miR-218-5p expressing group." (PMID 36831545, 2023). "Another explanation could be that in our study, the analysis was performed in the post-neoadjuvant surgical specimen, where there is significant tissue heterogeneity, and where the intensity of EGFR expression may be different from that in the primary tumour." (PMID 38273853, 2023). "Interestingly, of the clinicopathological parameters, only the tumor grade showed a significant correlation with the EGFR levels, as pronounced EGFR expression was observed more frequently in the samples from tumors at advanced stages." (PMID 36769112, 2023). "Therefore, in future, effective immunotherapy can be accomplished in EGFR mutant LUAD patients by improving the inhibitory tumor immune microenvironment (TIME)." (PMID 37671151, 2023). "A universal method to evaluate EGFR status in tumours should be adopted." (PMID 38414930, 2023). "AICAR reduced EGFR-mutant cell line-derived tumour formation in vivo." (PMID 36810913, 2023). "Anti-EGFR VHHs linked to a CPP (non-arginine) resulted in 1000 fold higher cytotoxic activity in tumor cells compared to the small molecular EGFR tyrosine kinase inhibitors in preclinical experiments." (PMID 37746282, 2023). "Four genes increased concordantly in EGFR-amplified tumours in both primary and recurrent samples: EEA1 (co-localising early endosomal antigen 1 with the EGFR–EGF complex as it enters intracellularly), IVD (isovaleryl-coA dehydrogenase), SEC61G (co-expressed with EGFR on chr 7p11), and EGFR itself." (PMID 36765632, 2023).